APP (amyloid beta precursor protein)
Diseases named in the same sentence as APP in open-access papers (continued):
Sharing a sentence is not in itself a finding about the gene and the disease.
Alzheimer disease (continued). "Amyloid β (Aβ) peptide is derived from the β-amyloid protein precursor (APP) and is the principal component of senile plaque cores in Alzheimer’s disease (AD) brains." (PMID 35241726, 2022). "APP, amyloid precursor protein, is known to form one of the most common components of amyloid plaques in Alzheimer’s disease, although its biological function is still uncertain." (PMID 35806237, 2022). "In this study we compared the recently developed TSPO tracer [18F]F-DPA, with [18F]DPA-714 and [11C]PBR28 by performing in vivo PET imaging on the same Alzheimer’s disease mouse model APP/PS1-21 (TG) and wild-type (WT) mice with all three radiotracers." (PMID 34542805, 2022). "In this present study, we investigated the impact of pharmacologically induced microglial renewal on pathology, microglial activation, and gene expression using both the 3xTg and APP/PS1 mouse models of Alzheimer’s disease." (PMID 35787714, 2022). "ADAM10 has an important role in the signaling of Notch and shedding amyloid precursor protein (APP) accompanying Alzheimer’s disease pathophysiology." (PMID 35335970, 2022). "APP regulates synaptic function and the proteolytic cleavage of APP releases neurotoxic Aβ, which is important in Alzheimer’s disease." (PMID 36589236, 2022). "To achieve both aims, we used the APP/PS1 Alzheimer's disease mouse model, paired with the bispecific anti-HIV-mAb mAbB12-scFab8D3 (B12-8D3) and wild type animals as controls." (PMID 36276653, 2022). "The animals had pathognomonic signs of Alzheimer’s disease in the brains like increased APP, soluble amyloid-beta, and insoluble amyloid deposits." (PMID 36330340, 2022). "Investment in genetically supported target-indication pairs was highly skewed, with 68% of trials and 84% of patient-years devoted to targeting Aβ (APP) in Alzheimer’s disease." (PMID 36271285, 2022). "And Pax6 expression is increased in the brains of APP transgenic mice and human Alzheimer’s disease patients." (PMID 35573291, 2022). "The production of Aβ from amyloid precursor protein (APP) protein through the amyloidogenic pathway is another well-established characteristic of Alzheimer’s disease." (PMID 35889382, 2022). "Accumulation of the neurotoxic proteolytic derivative of amyloid beta precursor protein (APP), amyloid-beta (Aβ) peptide, is proposed to be key to the pathogenesis of Alzheimer’s disease (AD)." (PMID 35992588, 2022). "Since 1995, more than 100 transgenic (Tg) mouse models of Alzheimer’s disease (AD) have been generated in which mutant amyloid precursor protein (APP) or APP/presenilin 1 (PS1) cDNA is overexpressed (1st generation models)." (PMID 35431779, 2022). "Secretase processing of mutant BRI2 leads to secretion and deposition of BRI2‐derived amyloidogenic peptides, ABri and ADan that resemble APP/β‐amyloid (Aβ) pathology, which is characteristic of Alzheimer's disease (AD)." (PMID 36102248, 2022). "The established causative mutations in the APP, PSEN1, and PSEN2 can explain less than 1%,Alzheimer’s disease (AD) patients." (PMID 35491795, 2022). "Amyloid precursor protein (APP) is a transmembrane protein that plays critical role in the pathogenesis of Alzheimer's disease (AD)." (PMID 35882892, 2022). "Amyloid precursor protein (APP) and its cleavage fragment Amyloid-β (Aβ) have fundamental roles in Alzheimer’s disease (AD)." (PMID 35360155, 2022). "Alzheimer’s disease (AD) is characterized by the deposition of amyloid-beta (Aβ) plaques from improper amyloid-beta precursor protein (APP) cleavage." (PMID 35163117, 2022). "Mutations in the tau gene (MAPT) lead to frontotemporal dementia (FTD), whereas mutations in the genes for the amyloid-β precursor protein (APP) and the presenilins (PSEN1, PSEN2) cause early-onset, dominantly inherited forms of Alzheimer’s disease (AD)." (PMID 35120450, 2022). "Amyloid precursor protein (APP), presenilin 1 (PSEN1), and presenilin 2 (PSEN2) are associated with autosomal-dominant early-onset Alzheimer's disease (AD)." (PMID 36555832, 2022).
Alzheimer disease (continued). "A recent study in APP mutant model of Alzheimer’s disease (AD) has shown that IF reduced hippocampal neuron hyperexcitability and ameliorated cognitive deficits in a SIRT3-dependent manner." (PMID 35562171, 2022). "The amyloid precursor protein (APP) processing pathway was altered in Alzheimer’s disease (AD) and contributed to abnormal amyloid-beta (Aβ) production, which forms insoluble interneuron protein aggregates known as amyloid plaques in the brain." (PMID 35614968, 2022). "For instance, the intestine of patients with Alzheimer’s disease (AD) revealed the expression of amyloid precursor protein (APP), and a plaque-like deposition in the enteric nervous system (ENS)." (PMID 36386153, 2022). "Dysbiosis or imbalance of gut microbiota in Alzheimer's disease (AD) affects the production of short-chain fatty acids (SCFAs), whereas exogenous SCFAs supplementation exacerbates brain Aβ burden in APP/PS1 mice." (PMID 36207740, 2022). "The biochemical evidence is overwhelming that hypercholesterolemia is an important causal factor in the pathogenesis of AD; moreover, cholesterol intracellularly influences Alzheimer’s disease APP synthesis and amyloid-beta formation." (PMID 36678510, 2022). "Experimental studies in transgenic mice overexpressing Aβ precursor protein (APP) have shown transmissibility of Aβ pathology after the intracerebral inoculation of Alzheimer's disease (AD) brain extracts." (PMID 34641980, 2021). "To investigate if NHE6/Slc9a6 deficiency contributes to APP processing by BACE1 in neurons, we used primary neurons derived from AppSwe (Tg2576) mice, an Alzheimer’s disease (AD) mouse model that overexpresses human APP with the ‘Swedish’ mutation." (PMID 34617884, 2021). "Administration of OLT1177, an NLRP3 inflammasome inhibitor, rescued cognitive impairment and neuroinflammation in an APP/PS1 mouse model of Alzheimer’s disease." (PMID 33534121, 2021). "As such, first-generation transgenic mouse models that overexpress proteins linked to familial AD (FAD), and mutant amyloid precursor protein (APP) and presenilin have been extensively used to study Alzheimer's disease." (PMID 34046506, 2021). "Amongst these molecular modifiers, the amyloid precursor protein (APP), best known for its involvement in Alzheimer's disease pathogenesis, has been shown to modulate disease progression in SOD1-G93A mice." (PMID 34476545, 2021). "Experiments on APPswe/PS1dE9 mice (Alzheimer’s disease model) suggested that colivelin treatment improve the cognitive and behavioural functions and reduced Aβ deposition in the hippocampus in APP/PS1 mice." (PMID 34445477, 2021). "CNVs, resulting from somatic recombination and selectively affecting the APP gene, have also been found to produce genomic or subchromosomal instability in the Alzheimer’s disease brain." (PMID 34069648, 2021). "In the APP/PS1 mutant mouse model of Alzheimer’s disease, orally administration of 3,4—dihydroxybenzoic acid reduced APP expression and Aβ deposition in hippocampal tissue while increasing learning and memory." (PMID 34578818, 2021). "Amyloid precursor protein (APP), involved in the development of Alzheimer’s disease in DS people, is at the origin of the amyloid deposit in the pancreas of diabetic patients, leading to tissue destruction and tissue inflammation." (PMID 33671490, 2021). "A more surprising finding was the enrichment for neuronally expressed genes, such as amyloid precursor protein APP, a gene causally implicated in Alzheimer’s disease." (PMID 34306034, 2021). "Aβ peptides are formed by the proteolytic cleavage of APP by α-, β-, and γ-secretases, and this processing pathway is also the source of neurotoxic Aβ, a major component of Alzheimer’s disease." (PMID 33926499, 2021). "The amyloid precursor protein (APP), one of the key transmembrane proteins associated with Alzheimer’s disease, undergoes a complex and competing series of proteolytic processing events." (PMID 33839158, 2021).
Alzheimer disease (continued). "Amyloid-β peptides (Aβ) are protein fragments obtained following the abnormal cleavage assisted by β- and γ-secretase of β-amyloid precursor protein (APP), responsible for the proteinopathy in Alzheimer’s disease (AD)." (PMID 34681235, 2021). "The epigenetic regulation is an important aspect of Alzheimer’s disease as the expression level of many key proteins such as APP, BACE1, Presenilins and ApoE are known to be under epigenetic regulation." (PMID 33962636, 2021). "BACE1 gene encodes an enzyme that cuts the amyloid precursor protein (APP) and produces amyloid beta peptides that cause amyloid plaque in the brains of patients with Alzheimer’s disease." (PMID 34306005, 2021). "These phosphorylations have been widely studied in the key proteins of the γ-secretase complex and even in the APP substrate, as well as their relationship with Alzheimer's disease, stability of complexes, and activity modulation." (PMID 34881055, 2021). "Even though the role of altered APP metabolism is clear in Alzheimer’s disease, little is known about its role in the brain during neurodevelopment." (PMID 34679416, 2021). "Future studies will be necessary to unravel the potential functional interdependence between T-type VGCCs, the GABAergic system and APP and its relevance in the aetiopathogenesis of Alzheimer’s disease." (PMID 33441788, 2021). "These enzymes have been extensively studied in Alzheimer's disease as they are responsible for the processing of APP in neurotoxic Aβ peptides." (PMID 33926496, 2021). "Decades of research indicate that alteration in proteolytic processing of APP is a crucial element toward progression of Alzheimer's disease (AD)." (PMID 33409475, 2021). "APP was identified as the hub gene in the CD-specific subnet, and it has an important role in the pathogenesis of Alzheimer’s disease (AD)." (PMID 34484291, 2021). "Due to its role in APP processing, γ-secretase has been investigated for the development of disease-modifying therapeutics for Alzheimer’s Disease (AD), amongst other γ-secretase related disorders." (PMID 35011410, 2021). "The scaffolding protein family Fe65, composed of Fe65, Fe65L1, and Fe65L2, was identified as an interaction partner of the amyloid precursor protein (APP), which plays a key function in Alzheimer’s disease." (PMID 34202290, 2021). "Patients with Down syndrome have the tendency to show early onset of Alzheimer’s disease, which indicate the overexpression of APP and SYNJ1 and subsequent decrease in PI 4,5-P2 levels." (PMID 33627135, 2021). "Supermeres are highly enriched with cargo involved in multiple cancers (glycolytic enzymes, TGFBI, miR-1246, MET, GPC1 and AGO2), Alzheimer’s disease (APP) and cardiovascular disease (ACE2, ACE and PCSK9)." (PMID 34887515, 2021). "In an APP/PS1 transgenic mouse model of Alzheimer's disease, inhibition of HDAC3 in the hippocampus alleviated microglial activation, which showed therapeutic potential for Alzheimer's disease." (PMID 34512154, 2021). "APP is a major component of vascular amyloid and plaque present in the brain tissue of patients with Alzheimer’s disease." (PMID 34445251, 2021). "It has been studied extensively in the context of Alzheimer’s disease, as it is directly involved in the production of toxic amyloid-β from the amyloid precursor protein (APP)." (PMID 34945766, 2021). "Rab1 is also involved in the transport and processing of amyloid precursor protein (APP) in Alzheimer’s disease." (PMID 34769517, 2021). "BACE inhibitors, which decrease BACE1 (β-secretase) cleavage of the amyloid precursor protein (APP) and subsequently reduce neurotoxic amyloid-β (Aβ) levels, have been in clinical trials for the treatment of Alzheimer’s disease." (PMID 34302009, 2021). "Amyloid β (Aβ) is a cleavage product of the amyloid precursor protein (APP) and a major component of amyloid plaques associated with Alzheimer’s disease toxicity." (PMID 33753171, 2021).
Alzheimer disease (continued). "In contrast, cerebrospinal fluid TMAO levels have been indicated as predictive of cognitive decline in Alzheimer’s disease, while suppression of microbial TMA/TMAO production improves cognitive function in the murine APP/PS1 model of Alzheimer’s disease." (PMID 34836554, 2021). "The expression levels of the genes for APP (Alzheimer’s disease marker), DYRK1A, DSCR1 (Down syndrome critical region 1), ETS2, and SOD1, all of which are located on chromosome 21, are dysregulated in trisomic cells." (PMID 34433490, 2021). "There are even notch-sparing gamma-secretase inhibitors which were studied in the context of Alzheimer’s disease, inhibiting APP preferentially relative to Notch1." (PMID 34945766, 2021). "Cleavage of APP by BACE1 and subsequent cleavage by γ-secretase leads to the generation of Aβ peptides that form Aβ plaques that are a pathological hallmark of Alzheimer’s disease." (PMID 33722254, 2021). "The most widely accepted model of Alzheimer's disease aetiology is the amyloid hypothesis, first postulated in 1992,6 and based on the observation that all early onset, dominantly inherited forms of the disease are caused by mutations that lead to the abnormal-processing of APP." (PMID 33977265, 2021). "The physiological function of APP is not fully understood but its metabolism, as a precursor of amyloid β peptides (Aβ), plays a central role in initiating Alzheimer’s disease (AD)." (PMID 34475508, 2021). "This last genotype represents a model for Familial Alzheimer’s disease as it expresses the mutated human presenilin 2 (PS2-N141I) protein, together with the human mutated (Swedish variant K670N, M671L)Amyloid Precursor Protein (APP)." (PMID 34440815, 2021). "An important implication of these changes is an overall destabilization of amyloid precursor protein (APP) in Alzheimer’s disease pathogenesis." (PMID 34249948, 2021). "This is reminiscent of the internalization of the amyloid precursor protein (APP) in Alzheimer’s disease that was reported to require LC3 mediated recruitment of AP2 for efficient clathrin mediated turn-over." (PMID 33717153, 2021). "Amyloid precursor protein (APP) is a protein-encoding gene associated with cerebral amyloid angiopathy and Alzheimer’s disease." (PMID 33478018, 2021). "Consistently, in Alzheimer’s disease patients, DKK1 is highly expressed and causes suppression of LRP6-amyloid precursor protein (APP)-mediated Wnt/β-catenin signaling, which results in accumulation of amyloid-β and synapse loss." (PMID 34589484, 2021). "All the mice studies except one were transgenic models of different conditions such as APP/PS1 mice for Alzheimer’s disease, Ts65Dn mice for Down’s syndrome and BTBR T + Itpr3tf/J mice for autism." (PMID 34201092, 2021). "For autosomal dominant early-onset Alzheimer's disease (EOAD), mutations in the APP, presenilin 1 (PSEN1), or presenilin 2 (PSEN2) gene sequence are a major risk factor, while the APOE4 allele is a major risk factor for late-onset Alzheimer's disease (LOAD)." (PMID 34122554, 2021). "For example, the upregulation of ADAM10 causes the α-secretase cleavage of amyloid precursor protein (APP) and has been considered as a useful therapeutic approach in Alzheimer’s Disease." (PMID 33413403, 2021). "Other human APP mouse models with Aβ produced in the brain can have more aggressive Alzheimer disease–related pathology and earlier onset cognitive impairments in a range of behavioral tests." (PMID 34525093, 2021). "One of the first approaches to lower APP and Αβ involved antisense oligonucleotides (AONs) injected in different transgenic Alzheimer's disease mouse models that resulted in modest behavioral improvement by decreasing APP protein levels." (PMID 34061681, 2021). "These two proteases, for their function in processing APP into amyloid beta fibrils, have been deeply studied in Alzheimer's disease." (PMID 33926496, 2021).
Alzheimer disease (continued). "We conclude that as reported in microglia in the APP/PS1 (amyloid precursor protein/presenilin 1) murine model of Alzheimer’s disease, upregulation of Ripk1 in both twitcher and SD mice, predominantly occurs in activated macrophage/microglia." (PMID 34172992, 2021). "Proteolytic processing of amyloid precursor protein (APP) plays a critical role in the pathogenesis of Alzheimer’s disease (AD)." (PMID 34948396, 2021). "For example, DYRK1A has been reported to phosphorylate a number of substrates in addition to NFaTs, exemplified by Thr212 in Tau protein, and Thr in amyloid precursor protein (APP), both associated with Alzheimer disease, and RNA polymerase." (PMID 34335466, 2021). "Reduced spine density in CA1 hippocampus basal dendrites was also observed in two transgenic amyloid precursor protein (APP) mouse models of Alzheimer’s disease, Tg2576 mice and APP/Lo mice." (PMID 33542194, 2021). "Increased amyloid-beta (Aβ) and amyloid precursor protein (APP) in the brains of Alzheimer’s disease (AD) patients are common pathological hallmarks mediating the disease progression." (PMID 34880748, 2021). "In a mouse model for Alzheimer disease (APP/Presenilin 1 mice expressing human mutant presenilin 1 and a chimeric mouse/human amyloid precursor protein (Mo/HuAPP695swe)) unilateral nephrectomy increased plasma and brain Aβ deposition and reduced Aβ in urine." (PMID 34204545, 2021). "A previous study indicated that HNRNP A1 has a role in Alzheimer disease because it is involved in the maturation of amyloid precursor protein (APP) mRNA." (PMID 34071140, 2021). "In Alzheimer’s disease, the proteolytic cleavage of APP by secretases results in the production of toxic amyloid β peptide (Aβ), which is prone to aggregation." (PMID 34443678, 2021). "This enzyme is a transmembrane aspartyl protease that is a critical participant in the cleavage of APP and generation of Aβ plaques, one of the pathological hallmarks of Alzheimer’s disease." (PMID 33722254, 2021). "Amyloid-β is a product of the chromosome 21 gene APP (amyloid precursor protein) and the extra copy or ‘dose’ of APP is thought to be the cause of this early-onset Alzheimer’s disease." (PMID 33707583, 2021). "BACE1 is a protease belonging to the β-secretase family and is thought to play an important role in Alzheimer's disease via the processing of amyloid precursor protein (APP) in neurotoxic Aβ peptides." (PMID 34926701, 2021). "Chr21 contains approximately 233 protein-coding genes, some of which, like amyloid precursor protein (APP) and dual-specificity tyrosine phosphorylation-regulated kinase 1A (DYRK1A), have been linked to an Alzheimer’s disease (AD)-like phenotype." (PMID 33660221, 2021). "Especially, GRIN1 and MAPK1 interacted with APP protein and located in the key point of the “Alzheimer’s disease” pathway." (PMID 33784489, 2021). "Therefore, we designed the in vivo experiments to investigate the effects of mild subclinical zinc deficiency on cognitive decline in the APP/PS1 mouse model of Alzheimer's disease and addressed whether any effects could be reversed by normalizing the levels of zinc." (PMID 33597269, 2021). "Autosomal dominant Alzheimer’s disease (ADAD), caused by mutations in presenilin 1/2 (PSEN1/2) or amyloid precursor protein (APP), is a valuable model for characterizing the molecular drivers of Alzheimer’s disease." (PMID 33892504, 2021). "Accumulating evidence has shown that abnormal cleavage of APP is a central process in the pathological mechanisms of Alzheimer’s disease (AD), and the Wnt/β-catenin pathway is dysfunctional in AD brains." (PMID 34650914, 2021). "The deposition of amyloid-beta (Aβ) through the cleavage of amyloid-beta precursor protein (APP) is a biomarker of Alzheimer’s disease (AD)." (PMID 33946401, 2021).